DKK3 (dickkopf Wnt signaling pathway inhibitor 3)
Diseases named in the same sentence as DKK3 in open-access papers (continued):
Sharing a sentence is not in itself a finding about the gene and the disease.
kidney disease (11 papers, 2020 to 2025). "By examining three single-nucleotide polymorphisms at the dkk3 gene locus, a significant association with eGFR was found, thereby indicating DKK3 to potentially modify kidney disease severity in ADPKD." (PMID 38186869, 2024). "Further research into the mechanism of DKK3 and its use as a diagnostic tool, alone or in combination with other biomarkers, could prove clinically useful for better understanding the pathology of kidney diseases and improving early detection and treatment." (PMID 33391006, 2020). "Two further studies included in this review focused on DKK3 as a biomarker in the context of contrast-mediated (CM) kidney disease." (PMID 37298105, 2023). "As a negative regulator of the Wnt/β-catenin signaling pathway, DKK3 plays an important regulatory role in many kidney diseases." (PMID 35174294, 2021). "Recently, the protein DKK3 gained attention as an emerging biomarker for cardiovascular and renal diseases." (PMID 33883651, 2021). "DKK3 may have potential as a urinary biomarker for kidney disease because it is secreted into the urine under tubular stress." (PMID 37298105, 2023). "The size of each subgroup (N = 100 in total, 20 subjects each) is low, nevertheless, to the best of our knowledge, this is the first study that comprehensively addressed the value of serum and urine Dkk3 as novel biomarker in patients within the whole spectrum of renal disease." (PMID 37510820, 2023). "Previously, urinary DKK3 levels were investigated in relation to renal function and renal diseases." (PMID 33883651, 2021). "Recent evidence suggests that urinary DKK3 may serve as a potential biomarker for monitoring kidney disease progression and assessing the effects of interventions." (PMID 33391006, 2020). "Notably, DKK3 has shown powerful clinical value and should be used in the clinic to predict the diagnosis of kidney diseases; however, multicentre trials are still needed." (PMID 33391006, 2020). "DKK3, whether in urine or tissue, may be a potential biomarker to monitor kidney disease progression and assess the effects of interventions." (PMID 33391006, 2020). "Taken together, DKK3, whether in urine or tissue, is a potential biomarker to monitor kidney disease progression and assess the effects of interventions." (PMID 33391006, 2020). "Here, we summarize recent novel findings regarding the implications for DKK3 in kidney diseases." (PMID 33391006, 2020). "Taken together, translational studies that assess and modulate DKK3 may lead to new avenues for the prognosis, prevention and treatment of kidney diseases." (PMID 33391006, 2020). "However, as ADPKD is a disease that affects multiple systems and DKK3 is expressed in various organs with measurable levels detected in plasma, it is possible that DKK3 could serve as an indicator not only for renal disease but also for the overall condition." (PMID 38186869, 2024). "The presence of DKK3 may serve as a biomarker of kidney diseases." (PMID 33391006, 2020). "Nevertheless, a role for DKK3 in CVD including HF and renal disease was suggested." (PMID 33883651, 2021). "In clinical studies, increased urinary DKK3 levels identified patients at high risk for short-term CKD progression, regardless of the cause of kidney disease, baseline kidney function and albuminuria." (PMID 33275197, 2021). "Moreover, adriamycin-induced nephropathy resulted in the up-regulation of DKK3 expression in the tubular, but not in endothelial compartments." (PMID 33391006, 2020). "It was suggested that DKK-3 may serve as a potential predictor for AKI and increased urinary DKK3 levels identified patients at high risk for short-term CKD progression, regardless of the cause of kidney disease, baseline kidney function and albuminuria." (PMID 40332103, 2025).
kidney disease (continued). "Interestingly, in subjects with no kidney disease at baseline, in those with the lowest UAE-values (according to UAE-tertiles) DKK3 blood plasma levels did independently predict for new-onset CKD, even when correct for a multivariable model including eGFR." (PMID 33883651, 2021).
infection (8 papers, 2014 to 2023). The state of being infected such as from the introduction of a foreign agent such as serum, vaccine, antigenic substance or organism. "In contrast, infection with the vector encoding Lef1 greatly augmented IFN-γ expression in DKK3-treated FoxO4-cKO cells compared with FoxO4-cKO cells under Th1-polarizing conditions, indicating that ectopic Lef1 expression in FoxO4-cKO cells could rescue IFN-γ expression after DKK3 treatment." (PMID 36106640, 2022). "Moreover, siRNA silencing of Wnt signaling components, including β-catenin, CK1, Fzd5, Fzd9, and LRP6, significantly decreases E. chaffeensis infection, while silencing Wnt antagonist Dickkopf-related protein 3 (DKK3) promotes infection." (PMID 36960039, 2023). "Of note, RNA silencing of antagonist DKK3 results in increased infection, while RNA silencing of canonical and non-canonical pathway components such as CK1, CAMKII, NFAT, and β-catenin significantly reduces infection." (PMID 31681283, 2019).
cardiovascular disease (4 papers, 2014 to 2025). "Dkk-3 has been demonstrated to be closely involved in the development and progression of cardiovascular disease." (PMID 31918729, 2020).
adenocarcinoma (2 papers, 2020 to 2024). A common cancer characterized by the presence of malignant glandular cells. "Levels of Dkk3 expression were higher in nested than in infiltrative adenocarcinomas (p<0.05)." (PMID 33425757, 2020).
prostate (2 papers, 2011 to 2021). "Furthermore, in the same work, the authors showed contrasting effects of DKK-3 inhibition in prostate stromal and epithelial cells, suggesting that extracellular factors can strongly influence prostate carcinogenesis." (PMID 34884726, 2021).
respiratory diseases (2 papers, 2020 to 2026). "We found a significant association of circulating Dkk-3 with HGS, which shows that Dkk-3 can be a useful tool to assess dynapenia in the elderly population with respiratory diseases." (PMID 33023021, 2020). "We found a modest-to-significant increase in the plasma markers of inflammation, oxidative stress and muscle damage, which had varying degrees of correlations with Dkk-3, CAF22 and selected micro RNAs (miRs) in respiratory diseases." (PMID 33023021, 2020).
hematologic malignancies (1 paper, 2017). "Inactivation of Dickkopf-3 (DKK3) is closely associated with a poor prognosis in various solid tumor and hematologic malignancies." (PMID 28969056, 2017).
DKK3 also shares sentences with these, for which no sentence is quoted: Hepatic fibrosis (4 papers); squamous cell carcinoma (4); esophageal adenocarcinoma (3); age (2); cervical squamous cell carcinoma (2); chronic obstructive pulmonary disease (2); renal cell carcinoma (2); testicular cancer (2); actinic keratosis (1); acute pancreatitis (1); Alport syndrome (1); atrial fibrillation (1); atrophic gastritis (1); autism spectrum disorder (1); autosomal dominant polycystic kidney disease (1); benign breast disease (1); brain tumors (1); cardiac disease (1); cataract (1); Cerebral ischemia (1); Cholecystitis (1); cholestasis (1); Cholestatic liver disease (1); chronic liver failure (1); clear cell renal cell carcinoma (1); cognitive decline (1); colorectal tumor (1); deficient (1); dermatitis (1); dyslipidemia (1).
A further 36 diseases each share a sentence with DKK3 in 1 paper.